KLF4 (KLF transcription factor 4)
Diseases named in the same sentence as KLF4 in open-access papers (continued):
Sharing a sentence is not in itself a finding about the gene and the disease.
meningioma (108 papers, 2013 to 2025). A generally slow growing tumor attached to the dura mater. "Somatic TRAF7 mutations, when they occur in conjunction with mutations in the KLF4 gene, are associated with secretory meningioma development." (PMID 41372821, 2025). "Histological subtype–specific mutations, such as KLF4/TRAF7 in secretory meningiomas and SMARCE1 in clear cell meningiomas, were also not supported by our assay." (PMID 40951339, 2025). "Numerous studies have reported that TRAF7 mutations are frequently found alongside KLF4 mutations in meningiomas." (PMID 40181456, 2025). "Secretory meningiomas, which make up approximately 3% of all meningiomas, are characterized by combined Kru ̈ppel-like Factor 4 (KLF4)K409Q and TRAF7 mutations." (PMID 38879686, 2024). "TRAF7 mutations have been described in approximately 20–25% of all meningiomas and often co-occur with mutations in KLF4 or AKT1, which are in turn both mutually exclusive to each other." (PMID 39273576, 2024). "Mutations in the genes AKT1, SMARCB1, and SMO are rare in cases of atypical meningiomas, and mutations in the genes KLF4 and TRAF7 are associated with an indolent clinical behavior, thus making these meningiomas have a low risk of progression." (PMID 39202270, 2024). "Meningiomas with KLF4 or PI3K pathway variants nearly always harbor a concomitant mutation in TRAF7, which occurs in the WD40-repeat region of TRAF7." (PMID 38730704, 2024). "KLF4-K409Q mutations are found in a subset of NF2 wild-type meningiomas and almost always cooccur with mutations in TRAF7." (PMID 38571886, 2024). "Krüppel-like factor 4(KLF4)/TNF receptor-associated factor 7(TRAF7) mutations can also be used to diagnose secretory meningiomas." (PMID 37529695, 2023). "The mutation of TRAF 7 is frequently associated with mutations of AKT1 (which encodes for a kinase that regulates cell proliferation) or KLF4, and this combination is often linked to grade 1 meningiomas." (PMID 37760490, 2023). "Clinical meningioma is frequently associated with KLF4 mutations and low expression of KLF4 RNA and protein." (PMID 37031197, 2023). "Of note, KLF4-mutated meningiomas exhibit higher sensitivity to mTOR inhibitors such as temsirolimus, underlining the potential role of the PI3K/AKT/mTOR pathway as potential treatment target in meningioma." (PMID 36181606, 2023). "The most significant gene overexpressed in KLF4 meningiomas relative to AKT1 meningiomas was tetraspanin TSPAN12, which encodes a member of the transmembrane 4 superfamily." (PMID 36937440, 2023). "Like TRAF7/KLF4-mutated meningiomas, also AKT1-mutated tumors are frequently found in the skull base." (PMID 36181606, 2023). "In the present study, we examined a mutation in the transcription factor KLF4 (KLF4K409Q) associated with secretory meningiomas." (PMID 35996584, 2022). "The K409Q mutation in KLF4 is found in ∼15% of meningiomas, and the mutated allele KLF4K409Q is the same in all affected patients and occurs together with TRAF7 missense mutations." (PMID 35996584, 2022). "In contrast to these mutations, the K409Q mutation in KLF4, found in a subset of meningiomas, was discovered in ZF1." (PMID 35996584, 2022). "Introducing KLF4 with K409Q mutation in this cell line would make it a good experimental model with which to study the role of KLF4K409Q in secretory meningioma development." (PMID 35996584, 2022). "Lastly, we detected FGF3 mRNA in primary human meningeal cells expressing KLF4K409Q and in human meningioma tumor specimens with a TRAF7/KLF4-mutated genotype." (PMID 35996584, 2022). "Secretory meningiomas have been defined based on combined pathogenic variants of KLF4 and TRAF7 mutually exclusive of the PI3K pathway or NF2." (PMID 33262459, 2021). "KLF4K409Q is the only mutation identified in the KLF4 gene associated with meningiomas, and like AKT1, it is commonly associated with TRAF7 co-mutation in meningiomas of the central skull base and sphenoid wings." (PMID 34638590, 2021).
meningioma (continued). "Apart from NF2 alterations in sporadic meningiomas, various oncogenic mutations in KLF4, SMO, TRAF7, PIK3CA, AKT1 and POLR2A are also found to be clinically actionable genetic events in meningiomas." (PMID 34722286, 2021). "Meningiomas with pathogenic variants involving KLF4 were more commonly identified in the skull base away from the midline." (PMID 33262459, 2021). "KLF4 mutations are nearly exclusively found in WHO grade 1 meningiomas and are often found with TRAF7 mutations." (PMID 33346248, 2020). "Here we report that the Krueppel like factor 4 (KLF4)-K409Q mutation in skull base meningiomas triggers a distinct tumor phenotype." (PMID 32245394, 2020). "For example, secretory meningiomas show frequent co-mutations of the KLF4 and TRAF7 genes, while clear cell meningiomas show SWI/SNF-related, matrix-associated, actin-dependent regulators of chromatin, subfamily e, member 1 (SMARCE1) mutations." (PMID 33014773, 2020). "The KLF4 P238S mutation from the M20 foramen magnum tumor was distinct from the usual hotspot K409Q mutation reported in meningioma, and was previously seen in diffuse large B cell lymphoma." (PMID 31963394, 2020). "Tumors with mutations in both TRAF7 and KLF4 are most often found in secretory meningiomas with TRAF7 mutant tumors having a predilection for the anterior skull base." (PMID 33346248, 2020). "Meningiomas with Krueppel-like-factor 4 (KLF4)/TNF receptor-associated factor 7 (TRAF7) mutation often locate in the medial skull base and v-akt murine thymoma viral oncogene homolog 1 (AKT1)/TRAF7 mutation in the anterior skull base." (PMID 33042832, 2020). "Previous data have shown that about 10–14% of meningiomas harbor the mutation KLF4-p.K409Q (KLF4K409Q)." (PMID 32245394, 2020). "Meningioma, a tumor that arises from the membranes surrounding brain and spinal cord, was among a top significant disease with differentially expressed genes Klf4 and Smarce1l associated with PEPs inhalation in rat blood." (PMID 31888290, 2019). "At the genetic level, KLF4 is mutated in ~12% of grade I meningiomas, virtually all of which are of the secretory sub-type and also harbor TRAF7 mutations." (PMID 31970090, 2019). "Meningioma with TRAF7 mutations can harbor mutations in KLF4 or AKT1 in 40% and 33% of cases, respectively." (PMID 30082628, 2018). "KLF4 mutation is always c.1225A > C (p.K409Q) and it is specific for meningiomas; 15.7% of grade I meningioma and 9% of all meningiomas combined harbor this mutation." (PMID 30082628, 2018). "In the non-NF2 meningiomas it was observed the frequent mutation of TRAF7, a proapoptotic ubiquitin ligase; a part of these meningiomas with mutated TRAF7 exhibited also KLF4 (a transcription factor involved in pluripotency) and AKT1 mutations." (PMID 30279357, 2018). "The tumor location changes according to the mutation type: anterior fossa, median middle fossa, or anterior calvarium for TRAF7/AKT1 and SMO mutated meningiomas; lateral middle fossa and median posterior fossa for TRAF7/KLF4-mutated meningiomas." (PMID 30279357, 2018). "For example, secretory meningiomas were driven exclusively by TRAF7/KLF4 co-mutations, while fibrous meningiomas were primarily associated with NF2 loss." (PMID 28195122, 2017). "Recently it was reported that KLF4 K409Q together with TRAF7 mutations were harbored in most secretory meningioma patients." (PMID 27531889, 2016). "It has been shown that KLF4 mutations were exclusive for secretory meningiomas so finding combined TRAF7/KLF4 mutation can serve in the diagnosis of secretory meningioma subtype." (PMID 27429002, 2016). "One approach may be to use gene-editing technology such as CRISPR-based systems to target and restore critical TRAF7 function, along with associated alterations like KLF4 point mutations involved in meningioma." (PMID 41372821, 2025).
meningioma (continued). "A better understanding of the molecular drivers of tumor progression and recurrence, such as the roles of NF2, SMO, AKT1, TRAF7, and KLF4 mutations, will facilitate the development of targeted therapies, potentially improving outcomes for patients with atypical and anaplastic meningiomas." (PMID 41007735, 2025). "Overall, TRAF7 alteration activates both tumor supportive (CDC42) and tumor suppressive (KLF4) pathways, and the co-occurrence of TRAF7 and KLF4 mutations allows for hyperactivation of Ras signaling as well as impaired tumor suppression, leading to meningioma growth." (PMID 41372821, 2025). "TRAF7 mutations in meningioma co-occur either with mutations in Kruppel-like factor 4 (KLF4) or in other genes, including v-Akt murine thymoma viral oncogene homolog 1 (AKT1) or phosphatidylinositol-4,5-bisphosphate 3-kinase catalytic subunit alpha (PIK3CA) variants." (PMID 41372821, 2025). "Interestingly, ISLR2, AMH, and lncRNA-GOLGA6A-1 transcription is controlled by several transcription factors including KLF4, which is linked to activating mutations of meningiomas." (PMID 38001599, 2023). "Likewise, KLF4 mutations seem to occur only in NF2-intact meningiomas and frequently co-exist with alterations of TRAF7." (PMID 36181606, 2023). "Additionally, TRAF7 mutations instigate meningioma growth by acting in combination with one of various co-mutations such as KLF4 and AKT1." (PMID 38001599, 2023). "The contribution of the meningioma-specific KLF4 mutation to tumorigenesis and mechanism of action is unknown." (PMID 35996584, 2022). "Whole-genome sequencing defined a unique mutation in KLF4 (KLF4K409Q) in human meningiomas." (PMID 35996584, 2022). "The relative impact of FGF3 on secretory meningiomas with KLF4 mutation remains unclear and deserves further study supported by a larger number of primary tumor samples." (PMID 35996584, 2022). "As an exception, one patient presented with a psammomatous meningioma with a POLR2A mutation, and another patient presented with an angiomatous meningioma with a KLF4 mutation, while yet another patient presented with an atypical meningioma with an AKT1 mutation." (PMID 33772057, 2021). "Hallmarks of secretory meningioma, hyaline periodic acid-Schiff-positive globules, and peritumoral edema, are suspected mechanistically to be associated to KLF4 signaling as a result of regulatory of cytokeratins 4 and 19 and activation of the bradykinin B2 receptor." (PMID 33262459, 2021). "Our initial hypothesis was that increased expression of KLF4 would direct the upregulation of hypoxic response genes in mutated meningiomas." (PMID 32245394, 2020). "Interestingly, in secretory meningioma, a specific genetic signature with simultaneous mutations in the KLF4 transcription factor and the TRAF7 E3 ubiquitin ligase has been found." (PMID 29983887, 2018). "In addition to the CDKN2A/CDKN2B genes, the KLF4 (Kruppel like factor 4) gene has also been recently reported to be mutated in meningiomas (particularly among secretory tumors) in association with lack of NF2 mutation." (PMID 25965831, 2015). "TRAF7 (along with NF2 and PI3K) associated meningiomas are more aggressive and recur at a significantly higher rate than other molecular subgroups of meningiomas (KLF4, POLR2A, and SMARCB1)." (PMID 41372821, 2025). "Over 80% of sporadic meningiomas fall into one of seven molecular subgroups, including NF2, TRAF7, SMARCB1, KLF4, and mutations in Hedgehog and PI3K pathways." (PMID 40637916, 2025). "Anterior parasagittal meningiomas are often driven by TRAF7, KLF4, or SMO mutations, while posterior ones are typically NF2-driven." (PMID 40569492, 2025). "TRAF7, SMO, AKT1, and KLF4 mutations, referred to as “non-NF2,” are typically found in lower-grade meningiomas, characterized by fewer chromosomal abnormalities, and generally result in better clinical outcomes." (PMID 40725113, 2025).
meningioma (continued). "The molecular characterization of meningiomas has led to the identification of key tumor-driving mutations, including NF2, POLR2A, TRAF7, KLF4, AKT1, SMARCB1, SMARCE1, and SMO." (PMID 39941893, 2025). "In our study, we analysed the most common driver mutations (NF2, AKT1, KLF4, and TRAF7) in meningioma by genomics describing co-occurrences and new mutations." (PMID 40562609, 2025). "Key genetic drivers, including mutations in NF2, SMO, KLF4, TRAF7, and chromosomal aberrations, allow for the stratification of meningiomas into distinct molecular subtypes, each associated with unique clinical outcomes and therapeutic vulnerabilities." (PMID 39941893, 2025). "Further frequent non-NF2 driver mutations in meningiomas include oncogenic mutations in TRAF7, KLF4, AKT1 and SMO, which are all mutually exclusive to NF2 mutations." (PMID 39273576, 2024). "In 2013, Clark and colleagues first described an association between WHO grade, histological subtype and the anatomical location of meningiomas with distinct molecular features, including mutations in TRAF7, KLF4, AKT1, SMO and NF2." (PMID 39273576, 2024). "FD is caused by a mosaic activating pathogenic variant in GNAS gene, and the development of sporadic meningiomas also has genetic predisposition including NF2, TRAF7, KLF4, AKT1 and TERT." (PMID 38287340, 2024). "Secretory meningiomas, a rare subtype associated with peritumoral edema, uniformly harbor co-mutation of TRAF7/KLF4." (PMID 38730704, 2024). "NF2 wild-type meningiomas frequently harbor mutations in TRAF7, KLF4, AKT1, PIK3CA, and SMO and are enriched in skull-base meningiomas." (PMID 38571886, 2024). "Additional frequent genomic alterations in meningioma include mutations in TNF receptor associated factor 7 (TRAF7), KLF transcription factor 4 (KLF4), and phosphatidylInositol-4,5-bisphosphate 3-kinase catalytic subunit alpha (PIK3CA)." (PMID 39726707, 2024). "GO analysis uncovered that the “extracellular matrix” gene set was the most representing in upregulated DEGs in AKT1 meningiomas, while KLF4 tumors upregulated DEGs important for “epidermis development” and “cell motility”." (PMID 36937440, 2023). "Mutations in Nf2, TRAF7, KLF4, AKT1, and SMO are present in approximately 80% of sporadic meningiomas." (PMID 37898750, 2023). "Since the majority of TRAF7 tumors harbor a gain-of-function mutation in a single amino acid position in either AKT1 or KLF4, AKT1E17K and KLF4K409Q appear to be the driving force behind TRAF7 meningioma growth." (PMID 36937440, 2023). "The authors used multi-omics data from human meningioma samples and cell lines to identify the functional roles of two genes, TRAF7 and KLF4, that are frequently mutated in meningioma." (PMID 37873876, 2023). "AKT1 meningiomas displayed increased expression of 1188 genes and decreased expression of 673 genes relative to KLF4 tumors." (PMID 36937440, 2023). "As a tumor suppressor, KLF4 affects apoptosis, proliferation, invasion and cell cycle of tumor cells during the malignant development of meningioma." (PMID 37031197, 2023). "The most frequent coding changes identified in non-NF2 meningiomas were missense mutations in TNF Receptor Associated Factor 7 (TRAF7), Kruppel-like factor 4 (KLF4), and RAC(Rho family)-alpha serine/threonine-protein kinase 1 (AKT1)." (PMID 36937440, 2023). "We used RNA sequencing (RNA-seq) to determine whole transcriptome profiles of twenty meningiomas with genomic alterations including NF2 inactivation, loss of chr1p, and missense mutations in TRAF7, AKT1 and KLF4." (PMID 36937440, 2023). "In agreement with observed mutations in AKT1 and KLF4, TRAF7 meningiomas segregated into two distinct clusters." (PMID 36937440, 2023). "In 2013, two separate landmark studies utilized whole genome and whole exome sequencing to uncover novel mutations in non-NF2 meningiomas including TRAF7 (TNF receptor associated factor 7), KLF4 (Krüppel-like factor 4), AKT1, and SMO (Smoothened)." (PMID 36840836, 2023).
meningioma (continued). "IMAT1 overexpression significantly increased proliferation and invasion of human meningioma cells expressing KLF4." (PMID 38001599, 2023). "MC ben-1 meningiomas were enriched in NF2 mutations while the MC ben-2 subgroup was enriched in non-NF2 mutations including TRAF7, AKT1, KLF4, and SMO." (PMID 36840836, 2023). "We found that VEGFA mRNA expression was almost 3-fold higher in KLF4 meningiomas compared to AKT1 tumors, in agreement with previous studies." (PMID 36937440, 2023). "We; thus, performed amplicon-based single-cell DNA sequencing on 7 samples of TRAF7 with KLF4 or AKT1, respectively, co-mutated meningiomas." (PMID 35984495, 2022). "Conversely, a larger study on 3031 meningioma samples from 514 individual cases has shown that TRAF7, AKT1, and/or KLF4 mutations were significantly associated with a lower risk of progression." (PMID 35565385, 2022). "A genomic study of 300 meningiomas showed mutations in TRAF7 in approximately 25% of all meningiomas, AKT1 mutations in 10-15% (affecting the PI3K signaling pathway) and KLF4 mutations in 10%." (PMID 36033542, 2022). "In their cohort of high grade meningiomas, most tumors were characterized by NF2 mutations, with very few tumors having mutations in TRAF7, KLF4, AKT1 and SMO, suggesting that high grade meningiomas have few targetable genetic mutations." (PMID 35402234, 2022). "Since 40-60% of sporadic meningiomas have a loss of NF2 expression, meningiomas can be molecularly categorized into NF2 mutants and non-NF2 mutants, with the latter predominantly comprised of TRAF7, KLF4, AKT1, SMO, and P13K mutations." (PMID 35712492, 2022). "TRAF7 is also one of four genes including KLF4, AKT1, and SMO, likely to be mutated in non-NF2 mutated meningiomas found at the skull base." (PMID 36686824, 2022). "TRAF7 and KLF4 mutations often co-occur in secretory meningiomas, with 40% of TRAF7-mutated meningiomas harboring a KLF4 mutation as well." (PMID 36686824, 2022). "Meningioma‐relevant mutations were present in 90/126 (71.4%) specimens including NF2, TRAF7, KLF4, SMO, AKT1,TERT promotor, ARID,SUFU, and PIK3CA mutations in similar frequencies compared to previous studies." (PMID 35213082, 2022). "In particular, AKT1, KLF4, SMO, or POLR2A mutations were significantly more frequent in meningiomas of paraxial mesodermal origin than in those of neural crest (p = 1.7 × 10–10) and dorsal mesodermal origin (p = 3.0 × 10–4)." (PMID 33772057, 2021). "From the embryological viewpoint, we found that the meningiomas harboring AKT1, SMO, KLF4, or POLR2A mutations were significantly associated with paraxial mesodermal origin." (PMID 33772057, 2021). "We comprehensively evaluated associations among tumor location, pathological diagnosis (histological type), and genetic alterations including AKT1, KLF4, SMO, POLR2A, and NF2 mutations and 22q deletion in 269 meningioma cases." (PMID 33772057, 2021). "AKT1, KLF4, SMO, or POLR2A mutations were significantly more frequent in meningiomas of skull-base lesions than in those of supra-tentorial lesions (p = 8.3 × 10–11)." (PMID 33772057, 2021). "Mutations in other known genes involved in meningioma pathogenesis such as AKT1 (E17K) and KLF4 (P238S) were marginally involved in one midline SB tumor, each from ED group #3." (PMID 31963394, 2020). "The clinical significance of the mutations of NF2, KLF4, and TRAF7 were proven in meningiomas, and studies have shown a significant association between mutations and specific locations." (PMID 32974148, 2020). "In the present study, all the sample groups had mutations in the meningioma-driver genes such as NF2, AKT1, SMO, TRAF7, and KLF4." (PMID 32742192, 2020). "Next, we focused on the most prevalent genetic alterations reported in meningiomas so far, including NF2, SMARCB1, as well as TRAF7, AKT1, SMO, KLF4, PIK3CA, and TERT in non-NF2 mutated meningiomas." (PMID 31470906, 2019).